PDE6B (phosphodiesterase 6B)
Diseases named in the same sentence as PDE6B in open-access papers (continued):
Sharing a sentence is not in itself a finding about the gene and the disease.
retinal degeneration (continued). "The 129S6 mouse is the background strain for transgenic 129S6/Tg2576 AD mice overexpressing hAPP and lacking the Pde6b rd1 retinal degeneration mutation." (PMID 26808326, 2016). "None of the pathogenic mutations in genes related to congenital retinoschisis (RS1) or retinal degeneration (USH2A, ABCA4, PDE6A, PDE6B, RPE65, etc.)were detected by targeted exome sequencing or WGS." (PMID 36980859, 2023). "Here, we compared the ability of hPRPCs to survive and integrate in normal and in rcd1/PDE6B mutant dogs, an IRD model that undergoes early-onset progressive retinal degeneration primarily affecting rods." (PMID 35905738, 2022). "In this study, we transplanted hiPSC-derived retinal cells into the subretinal space in Pde6b knockout rats, and examined the effect of the transplanted RPE and photoreceptor cells on retinal degeneration over a long period of times." (PMID 33828232, 2021). "However, negative findings have also been reported, as, for instance, diltiazem treatment failed to attenuate retinal degeneration in dogs with the same PDE6B defect as found in rd1 mice." (PMID 40631959, 2025). "Unlike rd1, in which Pde6b protein production and activity are not detected, rd10 mice are characterized by reduced Pde6b activity and relatively slower onset of retinal degeneration, starting at 4 weeks." (PMID 38139011, 2023). "The homozygous Pde6b−/− Prkdc−/− mouse model was named as NOD.SCID-rd1 where NOD.SCID indicates lack of T, B and NKT cells and rd1 stands for Pde6b−/− retinal degeneration model." (PMID 28258056, 2017).
retinitis pigmentosa (73 papers, 2010 to 2026). Retinitis pigmentosa (RP) is an inherited retinal dystrophy leading to progressive loss of the photoreceptors and retinal pigment epithelium and resulting in blindness usually after several decades. "Rd1 and rd10 mice are both retinitis pigmentosa models with PDE6β loss-of-function mutations, displaying rapid and slow rod degeneration, respectively." (PMID 38350962, 2024). "During mouse retinal development, the promoters of rod photoreceptor cell-specific genes Rho and Pde6b, associated with retinitis pigmentosa, exhibit high levels of DNA methylation at postnatal day 2 (P2) but low levels at P28." (PMID 37305686, 2023). "The purpose of this study is to identify novel variants in PDE6A and PDE6B genes and present its phenotypes in patients with retinitis pigmentosa in Chinese families." (PMID 35033039, 2022). "On the one hand, a mutation in the Pde6b gene, which will lead to the degeneration of rods and cones, simulating human pathologies of vision loss such as retinitis pigmentosa." (PMID 35897728, 2022). "In this retrospective, longitudinal, observational cohort study, we investigated the phenotypic and genotypic features of retinitis pigmentosa associated with variants in the PDE6B gene." (PMID 33673512, 2021). "The degeneration results from a mutation in Phosphodiesterase 6b (Pde6b), which is also mutated in some cases of the human disease retinitis pigmentosa." (PMID 30925931, 2019). "One of the most widely used models of retinitis pigmentosa, the rd1 mouse, harbors a spontaneous mutation in the phosphodiesterase 6β (PDE6B) gene, a common locus for mutations in retinitis pigmentosa." (PMID 26500497, 2015). "This study demonstrates, for the first time, a robust, long-term structural, functional and behavioural rescue of blind rd1 mice and supports the development of gene therapy for retinitis pigmentosa caused by mutations in PDE6B." (PMID 25613321, 2015). "Another commonly used model is the rd1 mouse, carrying a mutation in the Pde6b gene, is a commonly used model for retinitis pigmentosa (RP) due to its rapid and early photoreceptor degeneration, making it an efficient system for studying therapeutic interventions." (PMID 40239758, 2025). "To further confirm whether PEVsMH42-siCul7 serve as a promising strategy for RD therapy, we used Pde6βrd1/rd1 mutant mice which is a genetic mouse RD model with the same mutation of Pde6β as retinitis pigmentosa patients." (PMID 39267786, 2024). "The rd1 mutation disrupts the Pde6b gene, which is linked to retinitis pigmentosa in humans." (PMID 37880237, 2023). "The mutation of PDE6A causes retinitis pigmentosa 43, which affects the function of PDE6B." (PMID 35033039, 2022). "In this study, we present a novel mouse model of retinitis pigmentosa generated through pde6b gene knockout using CRISPR/Cas9 technology." (PMID 38139011, 2023). "In retinitis pigmentosa, the implicated genes that appeared across multiple studies include MERTK, PDE6B, CERKL, and ABCA4." (PMID 36836473, 2023). "Patients 1B, 2A, and 2B had mid-peripheral retinitis pigmentosa, concentric visual field ring scotomata in both eyes (OU), extinguished electroretinogram (ERG), and homozygous pathogenic variants in the PDE6B gene c.1540del PLeu514Trpfs*61." (PMID 36938204, 2023). "Here, we describe the development of a novel Pde6b-knockout Long–Evans (LE Pde6b KO) rat model that recapitulates key features of human retinitis pigmentosa (RP)." (PMID 36213678, 2022). "In conclusion, we have developed a novel LE Pde6b KO rat model for studying retinal degenerative diseases, such as retinitis pigmentosa." (PMID 36213678, 2022). "We expect these findings to have implications on the design of future PDE6B-related retinitis pigmentosa (RP) clinical trials." (PMID 33673512, 2021). "The Pde6b rd1 mouse model is one of the successfully used and widely characterized mouse models for retinitis pigmentosa." (PMID 28258056, 2017).
retinitis pigmentosa (continued). "It is crucial to comprehend the pathogenicity and functional significance of identified PDE6B polymorphisms to provide genetic information to families and facilitate participation in therapeutic trials for autosomal-recessive PDE6B-related retinitis pigmentosa." (PMID 39451534, 2024). "However, partial or entire gene deletions of PDE6B were only found in patients with retinitis pigmentosa, the autosomal recessive form of PDE6B-related disorders." (PMID 35440058, 2022). "We find that a retinitis-pigmentosa causing mutation in human PDE6G leads to the expression of a 3′UTR-encoded frameshift-isoform that is both destabilized and shows an inhibited ability to interact with its known binding partners PDE6A and PDE6B." (PMID 32727563, 2020). "Furthermore, stimulation of the mTOR pathway in mouse models of retinitis pigmentosa (Pde6b−/−, Pde6g−/− Rho−/− and Rho P23H) has been shown to prolong cone survival and may present as a potential treatment for patients with secondary cone degeneration." (PMID 35054919, 2022). "Mutations in PDE6B were reported previously to cause autosomal dominant congenital stationary night blindness or autosomal recessive retinitis pigmentosa, while mutations in PDE6A were reported to cause retinitis pigmentosa that is inherited in an autosomal recessive manner only (OMIM)." (PMID 35033039, 2022). "Very interestingly, the NDPK B-encoding mRNA is overexpressed in the degenerating retina of the rd/rd mouse, a retinitis pigmentosa model lacking PDE6B." (PMID 24040246, 2013). "Mutations in RHO and PDE6B, but not GNAT1, are also described in retinitis pigmentosa (RP)." (PMID 24760071, 2014).
retinal disease (17 papers, 2008 to 2025). "Pde6b plays a crucial role in controlling cGMP levels, and a buildup of cGMP has been linked to the death of rod photoreceptors in rd1 retinas, as well as to inherited retinal diseases connected to phototransduction." (PMID 38263197, 2024). "Photoreceptor cell death is a well-established characteristic observed in mouse models of retinal diseases, such as the rd10 (Pde6b) mouse model, which shows persistent accumulation of glial fibrillary acidic protein (GFAP) in Müller glia cells." (PMID 41224078, 2025). "Because the affected dogs did not share common alleles, we excluded single, fully penetrant mutations in six known canine retinal disease genes: BEST1, PDE6B and PDE6A, RPE65, NPHP4, and CNGB3." (PMID 25198798, 2014).
Blindness (11 papers, 2012 to 2024). Blindness is the condition of lacking visual perception defined as a profound reduction in visual perception. "The double mutant animal model Opn4−/− × Rd10, obtained from crosses between carriers of a mutation in the Pde6b gene and in the Opn4−/− gene, has been thoroughly characterized as a model of absolute blindness." (PMID 35897728, 2022). "We explored the functional consequences of the early manifestation of blindness in CBA/J mice which congenitally express the rd1 (rd1) mutation of the PDE6B gene that promotes loss of rods through apoptosis." (PMID 30535137, 2019).
autosomal recessive retinitis pigmentosa (10 papers, 2017 to 2026). Autosomal recessive retinitis pigmentosa (RP) is an autosomally recessive inherited retinal dystrophy leading to progressive loss of the photoreceptors and retinal pigment epithelium and resulting in blindness usually after several decades. "Phosphodiesterase 6B (PDE6B) variants often cause autosomal recessive retinitis pigmentosa, also known as rod–cone dystrophy." (PMID 39451534, 2024). "It has been observed that Pde6brd1 mice (rd1), which carry a spontaneous nonsense mutation in the pde6b gene, have a strong phenotypic similarity to patients suffering from autosomal recessive retinitis pigmentosa." (PMID 38139011, 2023). "Mutations in the phosphodiesterase 6B (PDE6B) gene are a rare cause of autosomal recessive retinitis pigmentosa (arRP)." (PMID 36938204, 2023). "In humans, PDE6B mutations are responsible for autosomal recessive retinitis pigmentosa (arRP) in about 4–5% of patients." (PMID 35409251, 2022). "For example, mutations in PDE6A and PDE6B are associated with autosomal recessive retinitis pigmentosa." (PMID 29088834, 2017). "The homozygous Pde6b-KO mouse model demonstrated clinical signs of autosomal recessive retinitis pigmentosa due to a two-nucleotide deletion in the pde6b gene, leading to a frameshift and nonsense codon in the 104 position." (PMID 38139011, 2023). "Pathogenic mutations in the PDE6B gene are known to cause autosomal dominant congenital stationary night blindness (adCSNB) or autosomal recessive retinitis pigmentosa (arRP); however, similar mutations in PDE6A are known to cause only autosomal recessive retinitis pigmentosa (arRP)." (PMID 36959549, 2023).
Retinal dystrophy (8 papers, 2016 to 2025). Retinal dystrophy is an abnormality of the retina associated with a hereditary process. "Within the spectrum of RP-related retinal dystrophy, several gene therapy studies have been published for the replacement of specific mutated genes, such as RPGR MERTK, RLBP1 and PDE6B." (PMID 37762059, 2023). "This explains why pathogenic variants in PDE6A (OMIM #180071), PDE6B (OMIM #180072) and PDE6G (OMIM #180073) cause predominantly rod-involving retinal dystrophies, whereas pathogenic variants in PDE6C and PDE6H (OMIM #600827 and #601190) lead to retinal dystrophies which predominantly affect cones." (PMID 37433860, 2023).
congenital stationary night blindness (5 papers, 2014 to 2024). "Of note, the PDE6B gene is also included in the deleted region; mutations in this gene can cause autosomal dominant congenital stationary night blindness-2 or autosomal recessive retinitis pigmentosa-40." (PMID 35440058, 2022). "Mutations in PDE6B cause recessive RP and dominant congenital stationary night blindness with vastly variable phenotypes." (PMID 32211407, 2020). "Integrated expression and transcription regulatory network genes, such as congenital stationary night blindness (CSNB) genes GRK1, PDE6B, and TRPM1, showed cell-specific expression and transcription characteristics in either rods or bipolar cells (BCs)." (PMID 39055259, 2024). "Six genes encoding major components of the phototransduction cascade (RHO, GNAT1, PDE6B, GRK1, and SAG) and the regeneration of the visual pigment (RDH5) are described in congenital stationary night blindness (CSNB) patients." (PMID 24760071, 2014).
Usher syndrome (5 papers, 2013 to 2022). A syndromic diseae characterized by the association of sensorineural deafness (usually congenital) with retinitis pigmentosa and progressive vision loss. "The family was found to segregate novel mutations of two different genes: myosin VIIA (MYO7A), which causes type 1 Usher syndrome, and phosphodiesterase 6B, cyclic guanosine monophosphate-specific, rod, beta (PDE6B), which causes nonsyndromic RP." (PMID 23882135, 2013). "While Usher syndrome etiology is classically regarded as stemming from genes that do not contain PDE6A, PDE6B, or PDE6G, researchers have yet to identify whether the mechanisms that underlie vision loss in Usher syndrome are identical to those present in non-syndromic RP." (PMID 29472945, 2018).
cone-rod dystrophy (4 papers, 2018 to 2025). Inherited retinal dystrophies that belong to the group of pigmentary retinopathies. "Proof-of-principle studies using RNAi-based approaches to knock down mutant transcripts have also been evaluated in mice for the treatment IRD associated with Prph2, Impdh1 (RP10), Guca1a (cone-rod dystrophy), and Pde6b (RP) with varying levels of success." (PMID 33815052, 2021). "Here, we present the initial results of a pilot study targeting zebrafish orthologs of five human genes linked to RP: PDE6A, PDE6B, PDE6G, ABCA4, and RHO (note, ABCA4 is also linked to cone-rod dystrophy)." (PMID 30186835, 2018).
night blindness (4 papers, 2021 to 2023). Inability to see clearly in dim light. "Nevertheless, the phenotypic analysis revealed no substantial differences between the two groups except for night blindness as a symptom that was noted to be more prevalent in the PDE6A-linked RP than in the PDE6B group." (PMID 36959549, 2023). "We identified five RP patients with PDE6A variants and three with PDE6B variants, all our patients reported night blindness as the first sign appeared from birth." (PMID 35033039, 2022). "Phenotypic analysis revealed no substantial differences between the two groups except for night blindness as a symptom that was noted to be more prevalent in the PDE6A than PDE6B group by another group." (PMID 35033039, 2022).
cystoid macular edema (3 papers, 2021 to 2024). An autosomal dominantly inherited cystoid macular edema manifesting with macular atrophy, strabismus and, sometimes, pericentral retinitis pigmentosa. "In the Korean RP cohort caused by PDE6B mutations, optical coherence tomography parameters revealed relatively frequent observations of epiretinal membranes and cystoid macular edema." (PMID 38785568, 2024). "Additionally, a PDE6B mutation, which is associated with cystoid macular edema, was detected in one patient." (PMID 36836473, 2023). "Epiretinal membranes and cystoid macular edema were frequently noted in the patients with USH2A (75.0%) and PDE6B (50.0%) variants, respectively." (PMID 34721897, 2021).
leukemia (3 papers, 2015 to 2017). A malignant (clonal) hematologic disorder, involving hematopoietic stem cells and characterized by the presence of primitive or atypical myeloid or lymphoid cells in the bone marrow and the blood. "These ocular phenotypes resembled those of rd1 mice, which are characterized by early onset and severe lose of photoreceptors owing to a murine leukemia provirus insertion in intron 1 and a point mutation in exon 7 of pde6b gene mapped on mice chromosome 5." (PMID 27186975, 2016).
breast carcinoma (2 papers, 2013 to 2025). "In this paper we show significant expression of PDE6B, PDE6C, and PDE6D, in human breast cancer cell lines and patients’ breast cancer tissues." (PMID 24683528, 2013). "Considerable expression of PDE6B protein was seen in all sixteen breast cancer tissue samples, regardless of what type of breast carcinoma they represented." (PMID 24683528, 2013).
glaucoma (2 papers, 2021 to 2024). Increased pressure in the eyeball due to obstruction of the outflow of aqueous humor. "Cataract surgery in patients with RP shows a link to the emergence of glaucoma, particularly in those with RPGR and PDE6B gene mutations, revealing a novel association with PDE6B mutations not previously documented." (PMID 38586746, 2024).
Leber congenital amaurosis (2 papers, 2015 to 2021). Leber congenital amaurosis (LCA) is a retinal dystrophy defined by blindness and responses to electrophysiological stimulation (Ganzfeld electroretinogram (ERG)) below threshold, associated with severe visual impairment within the first year of life. "Naturally occurring canine models exist for several IRDs, some of which have contributed to gene augmentation therapies in humans, such as the Rpe65 model for Leber congenital amaurosis (LCA), and the Pde6a and Pde6b models for autosomal recessive RP phenotypes." (PMID 34828377, 2021).
cataract (1 paper, 2024). Partial or complete opacity of the crystalline lens of one or both eyes that decreases visual acuity and eventually results in blindness. "And Pde6b and Nrl were respectively identified as potential modifiers in Fox3e3 (-/-) and S100a4 (-/-) mice, expediting the progression of cataract development." (PMID 38439070, 2024).
memory impairment (1 paper, 2021). "The Pde6b gene is thought to be crucial for early detection of memory impairments." (PMID 33597019, 2021).
retinal edema (1 paper, 2022). "As such, our LE Pde6b KO model can be utilized to investigate the pathophysiology of inner BRB breakdown in RP as well as to evaluate new therapies for the treatment of retinal edema in RP." (PMID 36213678, 2022).
Stroke (1 paper, 2023). Sudden impairment of blood flow to a part of the brain due to occlusion or rupture of an artery to the brain. "Of these, four (PDE4D, PDE3A, PDE3B, PDE6B) were ranked in the top 1% by the exome method for stroke." (PMID 37492104, 2023).
X-linked recessive disease (1 paper, 2024). X-linked recessive form of disease. "In detail, five autosomal dominant (AD) ophthalmic diseases caused by variants in ABCA4, CRYGD, MYOC, RPL1L1, and TGFBI, one AR disease caused by the PDE6B variant, and one X-linked recessive disease caused by the OCRL variant were determined as genetic causes." (PMID 38785568, 2024).
cancer (5 papers, 2013 to 2022). A tumor composed of atypical neoplastic, often pleomorphic cells that invade other tissues. "In colorectal cancer samples PDE6A and PDE6B genes were found to be hyper-mutated genes and all the mutations are enlisted in OASIS, a multi-omic data repository for cancer." (PMID 30962868, 2019). "Yet, data on the role of GSTM5, PDE6B, SGPP2, PDE1B, DGKB, and PLCG2 in cancer are still lacking." (PMID 33282950, 2020).
retinopathy (5 papers, 2018 to 2023). "The two murine retinopathy models used had different mutations in Pde6b: the severe rd1 and the milder rd10 models." (PMID 29765300, 2018). "The Pde6b-KO mouse line had a C57Bl/6 background, and rd1 mice originated from the C3H mouse line, so we hypothesized that this slight difference in retinopathy development could be due to alterations in the genetic background of these mice." (PMID 38139011, 2023). "In this light, the combination of CITED1 and PDE6B mutations could lead to the development of retinal disorders, explaining both the absence of disease-phenotype in hemizygous controls and the intrafamilial variability." (PMID 33302505, 2020).